TSC1 (TSC complex subunit 1)
Diseases named in the same sentence as TSC1 in open-access papers (continued):
Sharing a sentence is not in itself a finding about the gene and the disease.
Anxiety (7 papers, 2015 to 2023). Intense feelings of nervousness, tension, or panic often arise in response to interpersonal stresses. "We also observed a potential pattern of more depressed and anxious mood, and higher rates of anxiety and depressive disorders in association with TSC1 mutations." (PMID 30201051, 2018). "Thus, mice with conditional heterozygous Tsc1 knockout in Nkx2.1 inhibitory cells display a normal anxiety level and locomotion." (PMID 32375878, 2020). "Interestingly, individuals with TSC1 mutations showed higher rates of impulsivity, anxiety, depressed mood, hallucinations, psychosis, and of ADHD, anxiety and depressive disorders." (PMID 32733359, 2020). "In animal models, although chronic rapamycin treatment from postnatal day 8 to 40 improved anxiety- and depression- like behaviors in a model of Tsc1, daily rapamycin administration beginning at E12.5 resulted in hippocampal-dependent learning impairment in a mice model of Tsc2." (PMID 26248290, 2015). "Given that Tsc1 and Tsc2 form a complex for signal transduction and Tcs2 deletion increases anxiety, the impairment of Tsc1 mutant mice in the reversal of eyeblink conditioning is in line with our finding that an altered emotional response may limit behavioral flexibility in a mouse model of ASD." (PMID 36192805, 2022).
cardiac hypertrophy (7 papers, 2012 to 2025). "In another example, the loss of TSC1 in cardiac smooth muscle cells results in cardiac hypertrophy and death." (PMID 22916036, 2012). "In studies of hypertrophic cardiomyopathy (HCM), miR-451 was found to regulate cardiac hypertrophy and cardiac autophagy by targeting tuberous sclerosis complex 1 (TSC1)." (PMID 37510277, 2023). "Taken together, our findings indicate that miR-451 regulates cardiac hypertrophy and cardiac autophagy by targeting TSC1." (PMID 25209900, 2014). "In summary, our study reveals that miR-451 is one of the most down-regulated microRNAs in HCM and regulates cardiac hypertrophy and cardiac autophagy by targeting TSC1." (PMID 25209900, 2014). "Finally, our study unveiled that miR-451 negatively regulated cardiac hypertrophy and cardiac autophagy via targeting TSC1." (PMID 25209900, 2014). "Furthermore, overexpression of miR-451a could suppress cardiac hypertrophy and autophagy by targeting tuberous sclerosis complex 1 (TSC1)." (PMID 28624816, 2017). "The miR-451 level was found to be decreased in human cardiac hypertrophy and subsequent sudden cardiac death, regulating cardiac hypertrophy and cardiac autophagy by targeting TSC1, showing a negative correlation with left ventricular mass and becoming a potential therapeutic target for the disease." (PMID 36831306, 2023).
infantile spasms (7 papers, 2014 to 2024). A rare epilepsy syndrome characterized by onset of epileptic spasms in infants between 2 and 12 months of age, and rarely up to 24 months. "For example, in the TOSCA study, the rate of infantile spasms was higher in TSC2 patients than in TSC1 patients (47.3% vs. 23%)." (PMID 36232477, 2022). "Tuberous sclerosis complex (TSC) is a disorder of mTOR signaling caused by mutations in TSC1 and TSC2, associated with epilepsy (up to 80%), especially infantile spasms (IS) and high prevalence rates of ASD (up to 50%)." (PMID 34658944, 2021).
melanoma (7 papers, 2016 to 2025). A malignant, usually aggressive tumor composed of atypical, neoplastic melanocytes. "We report the first case of a collision tumor composed of adenocarcinoma and melanoma with a TSC1 mutation that objectively and durably responded to mTOR inhibition." (PMID 28302097, 2017). "In this study, we discovered that the loss of Tsc1 caused a decrease in the number of NK cells and that this decrease was strongly associated with the lung metastasis of melanoma." (PMID 27601261, 2016). "In this respect, TSC1 mutated melanomas seem to have a poor prognosis but may benefit from targeted therapy." (PMID 37373134, 2023). "TSC1 mutations are also rare in cutaneous melanomas and are more frequent in subungual melanomas." (PMID 37373134, 2023). "For example, in melanoma models, iNOS-generated NO can reversibly S-nitrosylate the TSC2 protein, disrupting TSC2/TSC1 dimerization, leading to mTOR activation and increased melanoma cell proliferation." (PMID 39737957, 2024). "Lastly, we analysed whether Tsc1 deletion affected the ability of NK cells to prevent the metastasis of B16 melanoma." (PMID 27601261, 2016). "Tsc1 deficiency in these mice led to severe defect in the anti-metastasis of B16 melanoma, even in the absence of T and B cells." (PMID 27601261, 2016). "Instead, TSC1 deficiency in DCs profoundly affected the CD8+ T-cell compartment, leading to substantial reduction in both naïve and memory–phenotype CD8+ T cells in the steady state, and severely compromised CD8+ T-cell activation in response to L.M. infection and melanoma challenge." (PMID 31433805, 2019).
bladder tumors (6 papers, 2011 to 2020). "More than half of all the bladder tumours show loss of an allele of TSC1." (PMID 21283818, 2011). "A very large proportion of bladder tumours lost an allele of TSC1." (PMID 21283818, 2011). "As TSC1 or TSC2 mutations occur in cancers, we sought to determine if the TSC2 loss-of-function expression signature was present in human bladder tumors since this tumor type often sustains inactivating TSC1 or TSC2 mutations." (PMID 28695825, 2017). "However, there has been no publication about the correlation between the PKC-alpha, JNK2, RICTOR, and TSC-1 in bladder tumor." (PMID 32802870, 2020). "Signature scores were greater in tumors having non-silent TSC1 or TSC2 mutations versus other bladder tumors indicating that these cancers have an identifiable gene expression signature derived from inactivation of TSC1 or TSC2." (PMID 28695825, 2017). "Interrogation of the TCGA cohort revealed that TSC1 and TSC2 mutant bladder tumors overexpressed LGALS3 versus other bladder tumors." (PMID 28695825, 2017).
chordoma (6 papers, 2009 to 2024). Chordomas are rare malignant tumors arising from embryonic remnants of the notochord in axial skeleton. "Mutation of tumour suppressor genes TSC1 et TSC2 is seen in patients with chordomas associated with Tuberous Sclerosis." (PMID 26391590, 2015). "Most chordomas are sporadic with a few familial brachyury T and syndromic (TSC1/TSC2) cases reported." (PMID 38700789, 2024). "Intriguingly, chordoma sometimes occurs in patients with tuberous sclerosis complex, which is characterized by loss of the mTOR negative regulators TSC1/2, further hinting at a role for the PI3K/mTOR pathway in chordoma pathogenesis." (PMID 36387127, 2022). "The genes TSC1 and TSC2, being of the mTOR pathway, have raised the possibility that this pathway is implicated in intracellular signalling for oncogenesis in chordomas." (PMID 26391590, 2015). "The chromosomal region 9q34.13, where the TSC1 gene is localized, is also frequently lost in sporadic chordomas." (PMID 22613809, 2011). "Generally, the consistent activation of AKT, the frequent activation of p70S6K and of mTOR, together with frequent loss of the TSC1 and PTEN genes, all suggest an important role for the PI3K/AKT pathway in chordoma." (PMID 22613809, 2011). "This study focuses on determining if there is evidence for the activation of PI3K/AKT/TSC1/TSC2/mTOR signalling in chordomas in view of existing therapeutic inhibitors." (PMID 19401700, 2009). "Chordoma also occurs in association with TSC, an autosomal dominant neurocutaneous syndrome characterized by abnormal tissue growth in multiple organ systems caused by inactivating germline mutations in either TSC1 or TSC2." (PMID 34070849, 2021). "In conclusion, the consistent activation of AKT, the recurrent activation of upstream EGFR and of downstream effectors like p70S6K and mTOR, together with frequent loss of TSC1 and PTEN gene loci, all indicate that the PI3K/AKT pathway is an important mediator of transformation in chordoma." (PMID 22613809, 2011). "However, our finding that AKT is activated in over 90% of chordomas argues that the tumour suppressor genes, TSC2 and TSC1, in sporadic chordoma are likely to be ‘inactivated’ not as a result of loss of heterozygosity but rather by phosphorylation of TSC2, at threonine 1462, by p-AKT." (PMID 19401700, 2009).
Cowden syndrome (6 papers, 2008 to 2021). "Oncogenic aberrations in these pathways are implicated in a wide spectrum of malignancies and are present in many syndromes associated with germline mutations in CPGs including FAP(APC), PJS (LKB1); Cowden syndrome (PTEN), and TSC (TSC1/2)." (PMID 33987182, 2021). "In support of this idea, epileptic seizure or macrocephaly are major symptoms seen in patients with tuberous sclerosis complex (TSC) mutations in either TSC1 or TSC2, or Cowden syndrome with PTEN mutations, respectively." (PMID 28686218, 2017). "Increased Akt/mTOR activity is consistent with deficiencies of FMR1, TSC1/2, or PTEN found in Fragile X, TSC, and Cowden syndrome and suggests that increased Akt/mTOR activity may have a role in the pathophysiology of the general ASD population and not limited to single ASD genetic mutations." (PMID 28361047, 2017). "Interestingly, BHD is a member of the hamartoma syndrome family that includes Cowden syndrome (CD, affected gene PTEN), Peutz-Jeghers syndrome (PJS, affected gene LKB1), and tuberous sclerosis complex (affected genes TSC1/TSC2)." (PMID 18974783, 2008). "As one of the hamartoma syndromes, BHD shares many clinical features (such as follicular hamartomas, mucosal fibromas, and internal malignancy) with Cowden syndrome (CD, affected gene PTEN), Peutz-Jeghers syndrome (PJS, affected gene LKB1), and tuberous sclerosis complex (affected genes TSC1/TSC2)." (PMID 18974783, 2008).
Infertility (6 papers, 2012 to 2025). "Sustained activation of mTOR in germ cells by genetic ablation of the Pten/Tsc1/Tsc2 causes untimely recruitment of primordial follicles leading to premature ovarian failure and infertility." (PMID 27036037, 2016). "A recent study indicated that deletion of Tsc1 in somatic cells of the reproductive tract caused infertility of female mice." (PMID 23335988, 2013). "Recently, we showed that conditional deletion of TSC1 in the female reproductive tract initiates oviductal epithelial cell dysplasia and causes blockage of embryo transport through the oviduct leading to infertility in mice." (PMID 22916036, 2012). "Conditional knockout of Tsc1 in somatic cells of the reproductive tract results in infertility in female mice." (PMID 23335988, 2013). "Oocyte-specific loss of TSC1 or TSC2 leads to premature ovarian failure and infertility in mice." (PMID 22916036, 2012). "In summary, the present study shows that depletion of Tsc1 in granulosa cells does not cause infertility in mice, but improves the reproductivity by stimulating folliculogenesis, ovulation and progressive accumulation of corpora lutea via increased activity of mTORC1." (PMID 23335988, 2013). "It is reported that mice lacking Tsc1 gene in oocytes show depletion of primordial follicles, resulting in premature ovarian failure and subsequent infertility." (PMID 23335988, 2013). "It is not clear whether specific depletion of Tsc1 in granulosa cells contributes to the fertility/infertility in the Tsc1flox/flox; Amhr2-cre female mice, because of the wide expression of Amhr2-cre in some somatic cells of the reproductive tract." (PMID 23335988, 2013).
liver cancer (6 papers, 2012 to 2025). An epithelial or non-epithelial malignant neoplasm that arises from the liver. "We developed an inducible liver cancer mouse model by knocking out the tumor suppressors Pten and Tsc1." (PMID 41142754, 2025). "Although Pten and Tsc1 single liver-specific knockout mice developed liver cancer after 40 weeks of age, Pten/Tsc1 double knockout mice developed HCC by 20 weeks." (PMID 32764389, 2020). "In conclusion, we demonstrate that HBx deregulates TSC1/mTOR signaling through IKKβ and renders liver cancer cells more sensitive to TNF-α stimulation in activating mTOR downstream S6K1 activity through IKKβ signaling." (PMID 22848663, 2012). "A previous study revealed that GCS was upregulated accompanied by a high level of GlcCer in the liver cancer of the mice lacking Tsc1 and Pten specifically in the liver, and the ratio of GlcCer/Cer was elevated." (PMID 35637196, 2022). "In addition, TSC1 overexpression resulted in poor outcomes in liver cancer patients (p < 0.05), but DCAF7 and EPS15 might not be associated with poor outcomes in liver cancer patients (both p > 0.05)." (PMID 35655269, 2022).
neurocutaneous disorder (6 papers, 2009 to 2025). "Tuberous sclerosis complex (TSC) is a rare neurocutaneous disorder caused by changes in the TSC1 and TSC2 genes and is characterized by hamartomas that affect multiple organ systems due to the reduced inhibition of the mTOR pathway." (PMID 40572688, 2025). "Tuberous sclerosis complex (TSC) is a severe neurocutaneous syndrome that results from heterozygous mutations in either TSC1 or TSC2." (PMID 32617425, 2020). "TSC is classified as a neurocutaneous syndrome, or a phakomatosis (birth mark) disorder, with an incidence of about 1 in 6000 births, associated with two separate genes located on either chromosome 9 (TSC1) or 16 (TSC2)." (PMID 38671997, 2024).
renal fibrosis (6 papers, 2020 to 2025). A final common manifestation of a wide variety of chronic kidney diseases characterized by glomerulosclerosis and tubulointerstitial fibrosis. "On the one hand, decreased C/EBPβ expression in TSC1 cKO macrophages is involved in poor M2 polarization, which is strongly associated with renal fibrosis." (PMID 33767704, 2021). "It is reported that let-7i-5p promotes renal fibrosis by targeting tuberous sclerosis complex subunit 1 (Tsc1) to activate the mammalian target of rapamycin (mTOR) signaling in UUO mice." (PMID 36091385, 2022). "We also demonstrated that during the repair process of renal IRI, the depletion of TSC1 in macrophages decreased renal fibrosis by preventing M2 polarization." (PMID 33767704, 2021). "This study demonstrates that TSC1 deficiency in macrophages promotes M1 polarization to aggravate kidney dysfunction during the early phase of renal IRI and attenuates renal fibrosis during the repair stage resulting from reduced M2 polarization." (PMID 33767704, 2021). "Furthermore, the Lyz-TSC1 cKO mice showed attenuated renal fibrosis during the repair phase of IRI with decreased levels of M2 markers on macrophages in the operated kidneys, which was further confirmed in a cell model of hypoxia-reoxygenation (H/R) in vitro." (PMID 33767704, 2021). "Clinically, the level of TRIM6, TSC1/2, and NF-κB p50 was found closely related to renal fibrosis." (PMID 33634104, 2020). "The expression of TRIM6 promoted the ubiquitination of TSC1 and TSC2, thereby activating mTORC1 and downstream processes of ER stress and EMT in renal fibrosis models." (PMID 33634104, 2020). "With the severity of renal fibrosis score, the protein levels of TRIM6 and the nuclear translocation of p50 increased significantly, while the protein levels of TSC1 and TSC2 decreased significantly in the kidney tissues of the patients." (PMID 33634104, 2020).
rhabdomyoma (6 papers, 2014 to 2024). A benign mesenchymal tumor arising from skeletal or cardiac muscle. "Analysis of disease trajectories revealed a more diverse clinical outcome for TSC2 patients: however, a chronological association of rhabdomyoma, NDD and KD was most frequently observed for TSC1 patients." (PMID 35440050, 2022). "Tuberous sclerosis complex (TSC), caused by autosomal dominant mutations in either TSC1 or TSC2 that causes a plethora of cellular dysfunctions due to mTOR inhibition, has heart symptoms in the form of rhabdomyomas in addition to other organ involvements such as the skin and brain." (PMID 39241028, 2024). "Intracardiac tumour (rhabdomyoma), neurodevelopmental disorders (NDDs) and kidney disorders (KD) are common manifestations of TSC and have been linked with TSC1 and TSC2 loss-of-function mutations independently, but the dynamic relationship between these organ manifestations remains unexplored." (PMID 35440050, 2022). "The location of rhabdomyoma within the heart was also compared between TSC1 and TSC2 patients to evaluate whether their genotype impacted the preferential location CR development within different heart structures." (PMID 35440050, 2022).
Sepsis (6 papers, 2020 to 2024). Sepsis is defined as life-threatening organ dysfunction caused by a dysregulated host response to infection. "To determine the role of mTOR in ERS-induced CD4+ T cell apoptosis, we constructed a sepsis model with T cell-specific mTOR and TSC1 gene knockout mice." (PMID 35915740, 2022). "We used T cell specific-mTOR/tuberous sclerosis complex 1 (TSC1)-knockout mice to explore the roles of the mTOR pathway in modulating autophagy during sepsis." (PMID 35435531, 2022). "To further investigate if the mTOR pathway regulated T-bet expression in Candida sepsis, we used T-cell-specific mTOR knockout (Lck-mTOR) mice and T-cell-specific TSC1 knockout (Lck-TSC1) mice." (PMID 32431684, 2020). "However, Bax, caspase-3, and BIM were upregulated, the expression levels of Bax, caspase-3, and BIM were upregulated, the BCL-2 expression level was downregulated, and the CD4+ T cell apoptosis rate significantly increased in the lck-TSC1 sepsis mice." (PMID 35915740, 2022). "To verify this hypothesis, we used T cell-specific knockout mTOR and TSC1 mice to create sepsis models using the classical CLP method to observe the effects of mTOR on ERS and the apoptosis of mice CD4+ T cells and the potential molecular regulatory mechanism." (PMID 35759162, 2022). "Drawing from two distinct knockout models, namely T-cell-specific TSC1 knockout (TSC1-KO) mice and T-cell-specific mTOR knockout (mTOR-KO) mice, we investigated the mTOR pathway's regulatory function on the autophagy level of CD4+ T cells and CTLA4 accumulation in sepsis." (PMID 39104632, 2024). "Also, mice with T-cell-specific TSC1 deletion had lower expression of T-bet and CD4+ T cell count indicating that the expression of T-bet required mTOR to participate in the regulation, and the regulation affected the CD4+ T cell count in Candida sepsis." (PMID 32431684, 2020).